ZBTB20 (zinc finger and BTB domain containing 20)
Description:
May be a transcription factor that may be involved in hematopoiesis, oncogenesis, and immune responses. Plays a role in postnatal myogenesis, may be involved in the regulation of satellite cells self-renewal (By similarity).
Synonyms: DPZF; ZNF288; ODA-8S; DKFZp566F123; HOF; PRIMS
Tractability: PROTAC: UniProt records ubiquitination sites on it; ubiquitination databases record sites on it; its protein half-life has been measured.
Gene: Protein-coding gene on chromosome 3 (114,314,500 to 115,147,356, reverse strand). Ensembl gene ENSG00000181722.
Subcellular location: Nucleus
Subcellular location (Human Protein Atlas): Nuclear bodies; Nucleoplasm
Gene Ontology:
Molecular function: sequence-specific double-stranded DNA binding; DNA-binding transcription repressor activity, RNA polymerase II-specific; RNA polymerase II cis-regulatory region sequence-specific DNA binding; transcription cis-regulatory region binding
Biological process: cellular response to glucose stimulus; lipid homeostasis; negative regulation of transcription by RNA polymerase II; positive regulation of glycolytic process; positive regulation of lipid biosynthetic process; regulation of cytokine production; regulation of immune system process
Cellular component: nuclear body; nucleoplasm; cytoplasm; nucleus
Genetic constraint (gnomAD): Loss-of-function variants: 9 observed, 52.32 expected, observed/expected ratio (o/e) 0.17, 90% interval 0.1 to 0.3. The upper end of that interval is the gene's LOEUF score, 0.3, which puts it in group 1 of 6, group 1 being the genes least tolerant of losing a copy. Missense variants: 655 observed, 997.21 expected, observed/expected ratio (o/e) 0.66, 90% interval 0.62 to 0.7. Synonymous variants: 417 observed, 427.15 expected, observed/expected ratio (o/e) 0.98, 90% interval 0.9 to 1.06.
Gene-disease validity (ClinGen):
ClinGen rates the evidence that ZBTB20 causes each of these diseases.
Primrose syndrome (autosomal dominant): Definitive.
Homologues: Orthologues: chimpanzee ZBTB20 (99% identical), macaque ZBTB20 (99% identical), dog ZBTB20 (99% identical), rabbit ZBTB20 (99% identical), pig ZBTB20 (98% identical), mouse Zbtb20 (98% identical), guinea pig ZBTB20 (97% identical), rat Zbtb20 (97% identical), tropical clawed frog ZBTB20 (80% identical), zebrafish zbtb20 (61% identical). Paralogues in human: ZBTB45 (27% identical), ZBTB16 (13% identical), PRDM1 (12% identical), HIC1 (11% identical), PRDM14 (11% identical), ZNF296 (11% identical), HIC2 (11% identical), ZBTB7C (10% identical), ZBTB18 (10% identical), ZNF143 (10% identical), ZNF692 (10% identical), PATZ1 (9% identical), and 24 more.
Diseases named in the same sentence as ZBTB20 in open-access papers:
ZBTB20 is named in the same sentence as 93 diseases in open-access papers, as found by Europe PMC text mining. Sharing a sentence is not in itself a finding about the gene and the disease. The quoted sentences say what the papers report.
Primrose syndrome (14 papers, 2015 to 2026). "Heterozygous missense variants in ZBTB20 cause Primrose syndrome, while the gene was associated with stuttering through a recessive mode of inheritance." (PMID 40836029, 2026). "Lastly, heterozygous missense variants in ZBTB20 cause Primrose syndrome, a neurodevelopmental disorder characterized by intellectual disability, macrocephaly, unusual facial features and progressive features such as hearing loss and muscle wasting." (PMID 40836029, 2026). "It is worth noting in this context that mutations in Zbtb20 cause Primrose syndrome in humans, which can be associated with intellectual impairments and seizures." (PMID 33833046, 2021). "For example, it has been reported that mutations in ZBTB20 are associated with Primrose syndrome, a genetic disorder characterized by intellectual disability, autism, and other behavioral concerns." (PMID 34285142, 2021). "ZBTB20, located at 3q13.31, has been identified as the causative gene for Primrose syndrome (MIM #259050), which is associated with severe neurodevelopmental disorders." (PMID 34571966, 2021). "Pathogenic inherited variants in the ZBTB20 gene have a known association to Primrose syndrome, an autosomal dominant syndrome including intellectual dysfunction and specific morphological features, but no known cancer." (PMID 33827643, 2021). "Defects of ZBTB20 have been implicated in a wide range of NDDs, including chromosome 3q13.31 microdeletion and microduplication syndromes, Primrose syndrome, ID, and in ASD." (PMID 30281617, 2018). "The common region of overlap involves 5 genes and among them ZBTB20 is implicated in Primrose syndrome associated with several endocrine features and obesity (OMIM #259050)." (PMID 29441128, 2018). "Diseases associated with ZBTB20 in humans include Primrose syndrome and juvenile pilocytic astrocytoma." (PMID 28125592, 2017). "More importantly, missense mutations of ZBTB20 have been linked to Primrose syndrome, suggesting that transcription factor ZBTB20 is an essential element for neurological disorders." (PMID 27657167, 2016). "Patients with heterozygous microdeletions, microduplications, or single nucleotide variants in different regions of the ZBTB20 protein show variability in clinical features that include autism, ID, and a more severe phenotype in patients with Primrose syndrome." (PMID 30281617, 2018). "In this regard, haploinsufficiency of the zinc finger and broad complex, tramtrack, bric and brac domain-containing protein 20 (ZBTB20) leads to a prototypical clinical picture, referred to as Primrose syndrome, comprising severe ASD symptoms together with intellectual disability." (PMID 41729076, 2026). "Due to our previous observation of enhanced ZBTB20 expression in CA1 pyramidal neurons upon recombinant human erythropoietin (rhEPO) injections, we anticipated a mitigating effect through rhEPO treatment of Zbtb20 deficiency/Primrose syndrome." (PMID 41729076, 2026). "Interestingly, individuals with Primrose syndrome develop diabetes in adulthood, which is consistent with the role of Zbtb20 in pancreatic β cells regulating glucose metabolism and insulin secretion." (PMID 28327662, 2017). "Therefore, Primrose syndrome is unlikely to be caused by haploinsufficiency of ZBTB20 and is thought to be the result of the dominant negative effect of ZBTB20 mutations." (PMID 34571966, 2021).
gastric cancer (9 papers, 2016 to 2024). A primary or metastatic malignant neoplasm involving the stomach. "In the correlation analysis between clinical indicators and gastric cancer risk, we also found that the ZBTB20 polymorphic site rs9841504 and platelet showed a certain significant correlation (P=0.048)." (PMID 32936247, 2020). "Many scholars began to be interested in the association between the ZBTB20 gene single-nucleotide polymorphism and gastric cancer susceptibility, but the results of these studies are not always same." (PMID 32936247, 2020). "It provides new data supplement for the study of the association between ZBTB20 gene polymorphism and gastric cancer risk." (PMID 32936247, 2020). "In summary, we conducted a correlation study between the ZBTB20 SNPs and gastric cancer susceptibility in the Chinese Han population." (PMID 32936247, 2020). "The purpose of the present study was to determine the correlation between single-nucleotide polymorphisms (SNPs) of ZBTB20 and the risk of gastric cancer in Chinese Han population." (PMID 32936247, 2020). "Nevertheless, as far as we know, the present study is the first to find evidence of a correlation between ZBTB20 rs9288999 and gastric cancer risk." (PMID 32936247, 2020). "In summary, our study is the first to find that the rs9288999 of ZBTB20 has a potential association with reducing the risk of gastric cancer in the Chinese Han population." (PMID 32936247, 2020). "Those subjects with both the risk alleles MUC1 rs9841504 and ZBTB20 rs4072037 had a greater than 3-fold increased risk of gastric cancer." (PMID 27127881, 2016). "Because MUC1 rs4072037 and ZBTB20 rs9841504 increased gastric cancer risk in the whole population, they were used to predict the risk of gastric cancer among the Han Chinese." (PMID 27127881, 2016). "Despite some studies indicating an association between ZBTB20 and certain cancers such as liver cancer and gastric cancer, its connection with LUAD and the underlying mechanisms remain largely unknown." (PMID 39125654, 2024). "This study provides data supplements for the association between the ZBTB20 gene polymorphisms and the risk of gastric cancer in the Chinese Han population, and concludes that there may have certain association between the two." (PMID 32936247, 2020). "The results of our study showed that ZBTB20 rs9288999 was significantly associated with reducing the risk of gastric cancer among the study population, whether in the overall analysis or stratified analysis." (PMID 32936247, 2020). "Then, the correlation between ZBTB20 SNPs and GC susceptibility in Chinese Han population was assessed; it will expand the association data between ZBTB20 genetic variation and susceptibility of gastric cancer." (PMID 32936247, 2020). "Therefore, it is necessary to expand the scope of the study to analyze the correlation between ZBTB20 gene polymorphism and susceptibility of gastric cancer in different populations." (PMID 32936247, 2020). "Therefore, in our study, the Chinese Han population was used as the research object to conduct a ‘case–control’ study, then we analyzed the correlation between ZBTB20 gene polymorphisms (rs10934270, rs9288999, rs9841504, rs73230612) and gastric cancer risk." (PMID 32936247, 2020). "We conducted a case-control study comprising 116 patients with gastric cancer as well as 102 sex- and age-matched controls and confirmed that the SNPs MUC1 (mucin 1) rs9841504 and ZBTB20 (zinc finger and BTB domain containing 20) rs4072037 were associated with an increased gastric cancer risk." (PMID 27127881, 2016). "Combining the results of our study, we speculated that the polymorphic site ‘rs9288999’ may have regulated the expression of ZBTB20 through the IκBα/NF-κB signaling pathway, which made rs9288999 showed a significant association with reduction of gastric cancer risk in the Chinese Han population." (PMID 32936247, 2020).
gastric cancer (continued). "ZBTB20 was also found to promote the activity of NF-κB in the gastric cancer cells and human dental pulp stem cells." (PMID 33777314, 2021). "ZBTB is a transcriptional repressor and upregulation of ZBTB20 expression has been shown in gastric cancer tissue, while knock down leads to inhibited cell proliferation, migration and invasion." (PMID 33827643, 2021). "ZBTB20 could also promote the invasion of various tumor cells, including glioblastoma and breast and gastric cancers." (PMID 38673877, 2024). "There have been discussions on the association of polymorphisms in the ZBTB20 gene and risk of gastric cancer but no consensus has been reached." (PMID 33827643, 2021). "Some polymorphism sites are significantly associated with gastric cancer risk have been reported, but there was no research about the association between ZBTB20 and the risk of gastric cancer in Chinese Han population." (PMID 32936247, 2020). "And there were studies showed that overexpression of ZBTB20 can promote the proliferation, migration and invasion of gastric cancer cells, which may be regulated by the IκBα/NF-κB signaling pathway." (PMID 32936247, 2020). "Interestingly, one GWAS identified a SNP within the sequences of ZBTB20, other than the one reported in this study, that is significantly associated with the risk of non-cardia gastric cancer in the Han Chinese population." (PMID 29942513, 2018). "Based on a genome-wide association study from 3,279 individuals of Chinese descent, ZBTB20 rs9841504 (intron variant, C > G/T) on 3q13.31 was quickly identified as a new susceptibility locus for non-cardia gastric cancer (GC)." (PMID 38397429, 2024). "More interestingly, whereas MUC1 rs4072037, ZBTB20 rs9841504, and TYMS rs2790 were suggested to improve the risk of noncardia gastric cancer (mainly the diffuse type) by 5- to 8-fold (P < 0.05*)." (PMID 27127881, 2016).
hepatocellular carcinoma (8 papers, 2011 to 2024). A malignant tumor that arises from hepatocytes. "More interestingly, ZBTB20 expression is increased in human hepatocellular carcinoma (HCC) and associated with poor prognosis, the underlying mechanism of which remains unclear." (PMID 29700307, 2018). "Recently, it was found that HBV can integrate into the Zbtb20 gene, and an association was observed between the integration and Zbtb20 expression in patients with hepatocellular carcinoma (HCC)." (PMID 37762065, 2023). "The involvement of Zbtb20 in tumor biology is best studied in hepatocellular carcinoma, where it is a promising candidate as an immunohistochemical tumor marker or may be used in patient screening." (PMID 37762065, 2023). "Zbtb20 was shown to increase proliferation and migration and confer resistance to apoptosis in the contexts of many malignant tumors like hepatocellular carcinoma, non-small-cell lung carcinoma, gastric adenocarcinoma, glioblastoma multiforme, breast cancer, and acute myeloid leukemia." (PMID 37762065, 2023). "Moreover, overexpression of ZBTB20 has been recently described as a prognostic marker by promoting tumor growth of human hepatocellular carcinoma." (PMID 27446912, 2016). "In this study, the expression of ZBTB20 was significantly overexpressed in hepatocellular carcinoma (HCC) tissues." (PMID 26893361, 2016). "The aim of this study is to determine the potential clinical implications of ZBTB20 in hepatocellular carcinoma (HCC)." (PMID 21702992, 2011). "Similarly, ZBTB20 has been found to be an important poor prognostic factor in hepatocellular carcinoma owing to its elevated levels in HCC and importantly, metastatic recurrence rates were found to be higher in HCC patients with high ZBTB20 levels." (PMID 28378523, 2017).
glioblastoma (7 papers, 2021 to 2025). The most malignant astrocytic tumor (WHO grade IV). "mir-758-5p targets ZBTB20 expression, which reduces glioblastoma invasion, migration, and proliferation." (PMID 35966888, 2022). "ZBTB20 has also been shown to be involved in tumorigenesis of glioblastoma, liver cancer and lung cancer." (PMID 33827643, 2021). "Mechanistically, ZBTB20 promotes glioblastoma progression via the miR-758-5p/ZBTB20 axis or by itself, but the mechanism by which ZBTB20 exerts roles on glioblastoma progression remains unknown." (PMID 38397429, 2024). "This could indicate that ZBTB20 is nonfunctional in glioblastoma cells, or alternatively, that it has not yet exerted its regulatory effects on pathways associated with mitochondrial dysfunction after 24 h of treatment." (PMID 41241854, 2025).
breast carcinoma (6 papers, 2022 to 2024). "LncRNA SNHG8 promotes breast cancer progression and sponged miR-634, leading to the upregulation of ZBTB20." (PMID 37426414, 2023). "For example, it acts as a miR-634 sponge in breast cancer, enabling the expression of the ZBTB20 oncogene, thus triggering breast cancer progression." (PMID 35774512, 2022). "al. also verified that SNHG8 modulates miR-634/ZBTB20 axis to promote breast cancer progression." (PMID 35067159, 2022). "Higher protein and mRNA levels of Zbtb20 due to either forced Zbtb20 expression or to the silencing of Zbtb20 mRNA-interacting microRNAs (miR) were concomitant with increased proliferation in HCC, NSCLC, GBM, GAC, AML, and breast cancer." (PMID 37762065, 2023). "In breast cancer, the miR-634 binds to the 3′ UTR of Zbtb20 and lowers its mRNA levels." (PMID 37762065, 2023).
acute myeloid leukemia (5 papers, 2020 to 2024). Acute myeloid leukemia (AML) is a group of neoplasms arising from precursor cells committed to the myeloid cell-line differentiation. "Studies have shown that SFMBT2 can promote malignant proliferation of acute myeloid leukemia cells by regulating the miR‐582‐3p/ZBTB20 pathway." (PMID 39711442, 2024). "Up-regulation of LINC00641 contributes to cell growth and migration in acute myeloid leukemia through modulation on miR-378a/ZBTB20 axis." (PMID 32297639, 2020). "By contrast, ZBTB20 was verified as a direct target of miR-378a in acute myeloid leukemia (AML) cells, and the miR-378a/ZBTB20 is further under the modulation of a novel AML-related IncRNA LINC00641 to promote cell growth and migration." (PMID 38397429, 2024). "LINC00641 is a novel acute myeloid leukemia (AML)-related lncRNA whose knockdown prevents cell proliferation, invasion, and migration and promotes apoptosis by modulating the miR-378a/ZBTB20 axis in AML." (PMID 35832170, 2022).
autism (5 papers, 2017 to 2026). Persistent deficits in social interaction and communication and interaction as well as a markedly restricted repertoire of activity and interest as well as repetitive patterns of behavior. "Two ZBTB20 single nucleotide variants, located at the N-terminal and central regions of the protein and potentially conferring autism risk, altered dendritic spine morphology." (PMID 30281617, 2018). "Next, we examined the effect of three ZBTB20 variants putatively implicated in autism risk (P46R, G346V) and in patients with ID (A620V)." (PMID 30281617, 2018). "Notably, many autism-associated DEGs, such as Zbtb20 and Phf21a, exhibited pronounced dysregulation in deep layer excitatory neurons." (PMID 39604385, 2024). "In contrast to these autism-risk ZBTB20 variants, expression of A620V led to neurons with reduced apical arborization between 300–400 μm from the soma compared to ZBTB20-WT-expressing neurons (P < 0.05) and enhanced basal arborization 75–125 μm from the soma compared to ZBTB20-WT (P < 0.01)." (PMID 30281617, 2018). "Recently, defects of ZBTB20, a BTB and zinc finger domain containing transcriptional repressor, have been implicated in a wide range of neurodevelopmental disorders, including intellectual disability and autism." (PMID 30281617, 2018).